PAX8 (paired box 8)
Diseases named in the same sentence as PAX8 in open-access papers (continued):
Sharing a sentence is not in itself a finding about the gene and the disease.
ovarian carcinoma (continued). "Hence, we asked whether following PAX8 inhibition ITGB3 expression was modified also in normal Fallopian tube and in general in ovarian cancer cells." (PMID 31832016, 2019). "We initially surveyed PAX8 levels in a diverse array of cell lines, and chose to use KURAMOCHI as the model system because it expressed abundant PAX8 and represented archetypal high-grade serous carcinoma, the most prevalent and lethal histotype of ovarian cancer." (PMID 31050342, 2019). "Since PAX2 and PAX8 are expressed in the fallopian tube, and PAX8 expression is maintained in HGSC, the expression and regulation of PAX proteins may help to explain the source of ovarian cancer." (PMID 30096791, 2018). "Similarly, ASRGL1 (asparaginase like 1) is highly expressed in ovarian carcinoma and confers a selective growth advantage; accordingly, our data show that ASRGL1 is preferentially expressed in SKOV-3 cells where it is downregulated following PAX8 silencing." (PMID 27259239, 2016). "In addition, the authors observed that PAX8 was localized to the nucleus of non-ciliated epithelia in simple ovarian epithelial inclusion cysts and in 3 epithelial ovarian cancer subtypes (serous, endometrioid and clear cell)." (PMID 23425942, 2013). "In addition to PAX8, COPA complemented with pan-cancer analysis prioritized eight other lineage-restricted outliers (CDH6, CLDN16, FGF18, FOLR1, SLC34A2, SOX17, SPON1, WNT7A) displaying largely confined gene expression in ovarian cancer cell lines and tumor specimens." (PMID 31050342, 2019). "An RNA‐seq analysis of ovarian cancer cells, given or not given ADSC CM, reveals PAX8 is among the top 10 differentially expressed genes." (PMID 33830648, 2021). "However, neither line shows expression profiles of ovarian carcinoma markers consistent with ovarian endometrioid carcinoma: A2780 cells do not express CK7 and ER and only weakly express PAX8, and ES-2 cells do not express PAX8 or ER but weakly express CK7." (PMID 39878900, 2025).
renal cell carcinoma (56 papers, 2013 to 2026). "The role of PAX8 in the context of renal cell carcinoma is linked to angiogenesis, which supports tumor growth even under hypoxic conditions." (PMID 40506992, 2025). "PAX8 is a specific marker for distinguishing TFEB-associated renal cell carcinoma from epithelioid angiomyolipoma." (PMID 36550835, 2022). "Notably, within the metabolic dysregulation hallmark of renal cell carcinoma, PAX8 is implicated in activating metabolic genes via enhancer elements." (PMID 38928435, 2024). "For the distinction between renal cell carcinomas and urothelial carcinomas, sensitivity was 86.7% and specificity 91.3% for PAX8, while sensitivity was 82.7% and specificity 99.8% for CDH16." (PMID 39105782, 2024). "Namely, if the TFE3 translocation occurs in a renal tubular stem cell, the neoplastic transformation will produce a renal cell carcinoma expressing PAX8 and CD10 (i.e., markers positive in the proximal tubule of the kidney)." (PMID 39410016, 2024). "For example, the occurrence of an SFPQ::TFE3 translocation in a PAX8-positive renal tubular stem cell will give rise to renal cell carcinoma, which has a 78%, 38%, and 44% chance of staining for CD10, cathepsin K, and HMB45, respectively." (PMID 39410016, 2024). "Immunohistochemical markers that are most commonly used for the distinction of renal cell carcinomas include PAX8 and CAIX46–48." (PMID 37558687, 2023). "PAX8 cannot be utilised to distinguish between primary cancer from renal cell carcinoma (92% positive) and primary thyroid tumours such as papillary thyroid carcinoma, which stains for PAX8 100% of the time." (PMID 35328664, 2022). "Paired box 8 (PAX8) is a sensitive marker for ovarian and endometrial carcinomas, as well as for renal cell carcinomas with sensitivity approaching 90%." (PMID 35433771, 2022). "The diagnosis of renal cell carcinoma was confirmed by the diffuse and strong staining for renal cell carcinoma markers (Pax-8, RCC-1, and CD10)." (PMID 32908722, 2020). "Like other subtypes of renal cell carcinoma, Xp11 translocation renal cell carcinomas are positive for PAX8." (PMID 31382581, 2019). "Using Core Regulatory Circuitry analysis (CRC), we identify PAX8 as a candidate oncogene in Renal Cell Carcinoma (RCC) cells." (PMID 31431624, 2019). "Overwhelming evidence elucidated that PAX8 is a efficacious marker to distinguish serous ovarian tumor, metastatic müllerian carcinomas, renal cell carcinoma." (PMID 29997452, 2018). "They did not express CD30, α-fetoprotein, p63, placental alkaline phosphatase (PLAP), surfactant B, napsin-A, CD10, pax-8, thyroglobulin, or renal cell carcinoma." (PMID 25442640, 2014). "Among the 22 metastatic cancers in a cancer control group, one showing PAX8+/Calretinin- represented a renal cell carcinoma, which is known to have such phenotype." (PMID 23958394, 2013). "The biopsy showed nests of epithelioid cells with clear cytoplasm and delicate vasculature, and immunohistochemical (IHC) staining demonstrated strong positivity for paired box gene 8 (PAX8), renal cell carcinoma (RCC) marker, and CD10, supporting renal origin." (PMID 41769517, 2026). "In metastatic ccRCC, commonly expressed immunohistochemical markers include CD10, PAX-2, PAX-8, human kidney injury molecule-1 (hKIM-1), renal cell carcinoma monoclonal antibody (RCCma), von Hippel–Lindau (VHL) tumor suppressor gene products, EMA, E-cadherin, and S-100 protein." (PMID 39931206, 2024). "Because PAX8 is a common marker of renal cell carcinoma, the carcinoma was suspected to be metastatic renal carcinoma; however, no renal primary tumor could be identified." (PMID 37966258, 2023). "Renal cell carcinoma was suspected based on PAX-8 immunoreactivity." (PMID 34449584, 2021). "While most PAX8+ and PAX2+ carcinomas are rarely confused with melanoma, cases of MiTf family altered renal cell carcinoma (MiTF-RCC) may pose a diagnostic challenge owing to the frequent patchy expression of melanocytic markers." (PMID 34449584, 2021).
renal cell carcinoma (continued). "Although cases of pituitary metastasis have been reported from PAX8-mutated renal cell carcinoma, PAX8 mutations have not been reported in primary pituitary pathologies." (PMID 34925233, 2021). "PAX8 is a known activator of metabolic genes in renal cell carcinoma." (PMID 33842927, 2021). "Additionally, ceruloplasmin is a predictive biomarker of PAX8 activity, and renal cell carcinoma (RCC) patients with high ceruloplasmin expression have a poor survival rate independent of genetic aberrations." (PMID 34413268, 2021). "Among the 22 metastatic cancers into the pelvis, one case with PAX8+/Calretinin- represented a renal cell carcinoma and the remaining 21 PAX8-/Calretinin- metastatic cancers were either breast metastasis (n = 4) and the metastasis from gastrointestinal tract (n = 17)." (PMID 23958394, 2013). "However, one thing we would like to emphasize here is that PAX8 can be also positive in renal cell carcinoma and benign Müllerian epithelia." (PMID 23958394, 2013). "In renal cell carcinomas (RCC), PAX8 promotes tumor growth through regulation of the E2F1-RB pathway." (PMID 27129161, 2016). "Our diagnosis also excluded sarcomatoid transformation of renal cell carcinoma and urothelial carcinoma through CA9, Pax-8, GATA3, P63, and P40." (PMID 40978053, 2025). "Other markers, such as PS100, MelanA, HMB45, SOX10, Chromogranin, Synaptophysin, CD56, PAX8 and a large panel of cytokeratins (CK7, CK20, panCK, MNF116), were all negative (not shown), eliminating melanoma, PEComa and carcinoma (notably renal cell carcinoma)." (PMID 38643139, 2024). "On the contrary, clear cell RCC stains positive for a variety of markers such as vimentin, galectin-3, CD10, CAIX, renal cell carcinoma (RCC), PAX-8, and epithelial membrane antigen (EMA)." (PMID 37990226, 2023). "PAX8 is expressed in several tumors of the urogenital system, such as in the majority of pediatric Wilms tumors, ~80% of renal cell carcinomas (RCC), and nephrogenic adenomas." (PMID 35806410, 2022). "The renal tubular transcription factor PAX8 and other renal markers, such as CD10 and renal cell carcinoma marker (RCC-Mat), are consistently positive." (PMID 34917511, 2021). "For instance, a renal cell carcinoma metastasis consists of sheets of bland clear cells in a vascular stroma (typically RCC, CD10, PAX8 positive)." (PMID 30693455, 2019). "if both renal cell carcinoma and lung adenocarcinoma are in the differential diagnosis based on morphology and/or clinical history a broad IHC panel including TTF-1, PAX-8 and vimentin should be applied for a definitive diagnosis." (PMID 25889632, 2015). "Renal cell carcinomas (RCC) stained positive for PAX8 in 90% of the cases studied and 100% of normal kidney samples stained PAX8-positive." (PMID 23425942, 2013). "In this case, negative immunoreactivity for pancytokeratin and PAX8 as well as lack of more dedicated vasculature excluded the diagnosis of renal cell carcinoma." (PMID 39568313, 2025). "However, it is noteworthy that PAX2 was found to be reactivated in renal cell carcinoma and that around 90% of renal cell carcinoma patients have high PAX2 and PAX8 expression levels." (PMID 38928435, 2024). "The combination of PAX8 and CDH16 positivity has high specificity for renal cell carcinoma." (PMID 39105782, 2024). "The evaluation of large cohorts of urinary bladder and renal cell carcinomas, as well as ovarian and endometrial cancers, did not suggest a major clinical and prognostic impact of PAX8 expression in these entities." (PMID 39105782, 2024). "Renal cell carcinoma with spindle cell change was excluded because the tumor cells were negative for PAX8." (PMID 36545560, 2022). "The renal tumor is immunoreactive for RCC (renal cell carcinoma marker), PAX8, and CD10, which were all negative in the CCCs investigated here." (PMID 35094698, 2022).
renal cell carcinoma (continued). "PAX8 immunostaining and CD68 (PG-M1) negativity support the diagnosis of TFEB-rearranged renal cell carcinoma, whereas pure epithelioid PEComa/epithelioid angiomyolipoma has the opposite immunoreactivity, being negative for PAX8 and positive for CD68 (PG-M1)." (PMID 34069976, 2021). "In our case, the tumor did not stain for PAX8, as well as carbonic anhydrase and keratins, effectively ruling out a diagnosis of renal cell carcinoma." (PMID 34925233, 2021). "Metastatic clear cell renal cell carcinomas are positive for PAX8, carbonic anhydrase IX (CAIX), and renal cell carcinoma marker (RCC-Ma)." (PMID 38672619, 2024). "The tumors cells were positive for p63 and focal CD10, negative for renal cell carcinoma markers RCC and PAX-8, and negative for myoepithelial marker calponin, melanoma markers S100 and HMB-45, and D2-40." (PMID 25685571, 2015). "PAX8, pan cytokeratin, CD10 negativity helps in ruling out renal cell carcinoma which is further substantiated by the absence of a renal mass on radiology." (PMID 37218666, 2024). "PAX8 and CD68 (PG-M1) are useful in differentiating them: CD68 (PG-M1) is reportedly positive and PAX8 negative in renal epithelioid-AMLs, whereas MiT family renal cell carcinoma is negative for CD68 (PG-M1) and positive for PAX8." (PMID 36740682, 2023). "Tumor cells were diffusely positive for CK7, EMA, and inhibin, while they were negative for CK20, P63, CK 5/6, CD10, renal cell carcinoma (RCC), TTF1, PAX8, CEA, and GATA3." (PMID 37261186, 2023). "Pathological examination revealed morphological and immunohistochemical findings in line with metastatic renal cell carcinoma, including positive staining for AE1/AE3 vimentin and CD10, partial positive for RCC, PAX-8, and negative staining for inhibin, CgA, and CA9, the index of Ki-67 is 5%." (PMID 34397852, 2021). "In these challenging cases, PAX8 (positive in TFE3-rearranged renal cell carcinoma and negative in pure epithelioid PEComa) and CD68 (PG-M1) (negative in TFE3-rearranged renal cell carcinoma and positive in pure epithelioid PEComa) are useful markers to reach the proper diagnosis." (PMID 39410016, 2024). "The expression of Pax8 was positive, but the expression CK7 and HNF1β was positive and that of CD10 and ER was negative, which indicate that the tumor has the feature of clear cell carcinoma of ovary, not renal cell carcinoma nor cholangiocarcinoma." (PMID 30117003, 2018). "The expression of Pax8 was positive, but the expression CK7 and HNF1β was positive and that of CD10 and ER was negative, which indicate that the tumor has the feature of clear cell carcinoma of the ovary, not renal cell carcinoma nor cholangiocarcinoma." (PMID 30117003, 2018).
follicular thyroid carcinoma (43 papers, 2004 to 2025). "PAX8/PPARG rearrangements are present in classic follicular carcinoma, follicular-variant-PTC and OCC, suggesting potential implications in tumor evolution, invasion and metastasis." (PMID 38277563, 2024). "A unique molecular characteristic linked to follicular thyroid cancer is the rearrangement of PAX8/PPARγ." (PMID 38501105, 2024). "Four molecular alterations, BRAF and RAS point mutations, and RET/PTC and PAX8/PPARγ rearrangements, are the most frequent causes of thyroid papillary and follicular carcinomas." (PMID 29721199, 2018). "PAX8/PPARγ mutations were found in one follicular carcinoma and two follicular adenomas, respectively." (PMID 26695504, 2016). "ENO3 is another cancer-related gene, associated to the PAX8-PPARG fusion protein in thyroid follicular carcinomas, and upstream regulation of PPARs and PPAR-related pathways was detected in the present study." (PMID 26492889, 2015). "PPARγ has also been linked with thyroid pathology since the discovery of a PAX8/PPARγ rearrangement in follicular thyroid carcinomas." (PMID 22654559, 2011). "There was a subsequent lull in the discovery of genetic mutations in thyroid cancer until the year 2000, when PAX8/PPARgamma translocations were found in follicular thyroid cancers." (PMID 24281099, 2010). "PAX8/PPARgamma mutations are typically associated with follicular thyroid cancers that present at an earlier age and with a high frequency of vascular invasion." (PMID 24281099, 2010). "Among all cancer, Differentiated Thyroid Carcinoma (DTC) holds a special place for TZDs, because follicular thyroid cancer is the only known neoplasm associated with a PPAR-γ fusion gene product with over 30% follicular thyroid carcinoma expressing PAX8/PPAR-γ." (PMID 34631571, 2021). "In conclusion the genetic rearrangements involving the PAX8 and PPARG genes are characteristic of thyroid follicular cancer and are associated with a more favorable prognosis and greater survival." (PMID 39744583, 2025). "Conversely, in primary follicular thyroid carcinomas, RAS variants and PAX8/Peroxisome Proliferator-Activated receptor γ (PPARγ) fusions are found in approximately 80% of cases." (PMID 36975488, 2023). "PAX8 expression can be found in 100% of papillary thyroid carcinomas, in 91–100% of thyroid follicular carcinomas, and in variable levels of up to 80% in anaplastic thyroid carcinomas." (PMID 35806410, 2022). "PPAR translocation and fusion with PAX8 was found to play a role in the pathogenesis of some types of follicular thyroid carcinoma." (PMID 34540435, 2021). "Follicular thyroid cancer and the follicular variant of papillary thyroid carcinoma are associated with mutually exclusive mutations of RAS or the paired box 8-peroxisome proliferator-activated receptor gamma (PAX8–PPARG) fusion oncogene." (PMID 34680488, 2021). "As expected, the BRAF V600E mutation and RET-PTC1 translocation were detected in the samples of papillary carcinoma only, whereas the PAX8-PPARγ translocation was found only in follicular carcinomas." (PMID 31660895, 2019). "The PAX8/PPARγ fusion oncogene has been identified only in follicular carcinomas and in a small fraction (about 13%) of follicular adenomas." (PMID 29721199, 2018). "The most frequent genetic alterations in follicular carcinomas are point mutations of RAS and the PAX8/PPARγ rearrangement." (PMID 29721199, 2018).